KLF16 (KLF transcription factor 16)
Diseases named in the same sentence as KLF16 in open-access papers (continued):
Sharing a sentence is not in itself a finding about the gene and the disease.
tumor (11 papers, 2018 to 2025). "The KLF16 mRNA encodes an evolutionarily conserved transcription factor that functions as either a tumor suppressor or an oncogene in a context-dependent manner." (PMID 39551759, 2024). "Considering that KLF16 is a transcription factor associated with tumor, we hypothesized that KLF16 might regulate Twist1 expression transcriptionally." (PMID 36639679, 2023). "Both KO and KD of KLF16 impaired colony formation, cell proliferation, and tumor growth in BLCA cells." (PMID 39551759, 2024). "Here, we demonstrate that KLF16 is essential for BLCA tumor growth and forms a reinforcing regulatory loop with MYC." (PMID 39551759, 2024). "The tumor volumes were obviously smaller in mice implanted with KLF16-depleted cells than in mice implanted with control cells." (PMID 36639679, 2023). "More importantly, stable knockdown of KLF16 largely attenuated the promoting effect of SF3B4 overexpression on tumor growth." (PMID 36639679, 2023). "KLF16 plays a tumor suppressor role in lung adenocarcinoma by inhibiting tumor cell proliferation and inducing apoptosis." (PMID 34823421, 2021). "Furthermore, the effects of co-regulating LEF1-AS1 and miR-328-5p and down-regulating KLF16 on tumor cells were further investigated." (PMID 41316360, 2025). "Knockout of KLF16 in vivo and in vitro inhibited tumor proliferation." (PMID 41316360, 2025). "In our study, we found that KLF16 is overexpressed and promotes tumor growth in BLCA." (PMID 39551759, 2024). "However, KLF16 has itself received much recent attention as a strong tumor promoting gene in multiple cancer types." (PMID 38067370, 2023). "Next, we detected epithelial and EMT marker gene expression in xenograft tumor tissues, and found that depletion of KLF16 in implanted cells dramatically reduced the expression of KLF16, Twist1, and mesenchymal markers vimentin, with an increase in the epithelial marker E-cadherin." (PMID 36639679, 2023). "It is therefore tempting to speculate that the down regulation of KLF9 and/or KLF13 in pre-neoplastic cells leads, in turn, to synergistic inductions in KLF16 expression and consequent tumor promotion." (PMID 38067370, 2023). "KLF16 expression in ccRCC tumor tissues was upregulated compared to that in adjacent normal tissues suggesting that circFOXO3 expression in ccRCC is transcriptionally upregulated by KLF16." (PMID 36072902, 2022). "Our study revealed the crucial role of the KLF16/MYC regulatory axis in modulating tumor growth and chemotherapy sensitivity in BLCA, suggesting that combining bromodomain inhibitors, such as OTX015 or ABBV-744, with DDP or gemcitabine could be a promising therapeutic intervention for BLCA patients." (PMID 39551759, 2024). "To determine whether the SF3B4-KLF16-Twist1 pathway is of pathophysiological relevance, we established a xenograft tumor model by implanting Caki-1 cells stably knocking down KLF16 and the cells stably overexpressing SF3B4, separately, or together into nude mice." (PMID 36639679, 2023). "Targeting this loop with bromodomain inhibitors, such as OTX015 and ABBV-744, suppressed the transcription of both KLF16 and MYC, resulting in reduced BLCA cell viability and tumor growth, as well as increased sensitivity to chemotherapy." (PMID 39551759, 2024). "Targeting this loop with bromodomain and extraterminal (BET) inhibitors, by impairing the transcription of KLF16 and MYC, leads to reduced cell viability, tumor growth, and increased sensitivity to chemotherapy in BLCA." (PMID 39551759, 2024). "More importantly, small and colocalized condensates formed by endogenous KLF16 and MYC were observed through super-resolution imaging in BLCA cell lines and tumor tissues." (PMID 39551759, 2024). "Such a tumor inductive scenario (if confirmed) can be approached in two ways, i.e., targeting the suppressors of KLF9 and KLF13 and targeting KLF16." (PMID 38067370, 2023).
tumor (continued). "Our study demonstrates that disrupting the KLF16/MYC loop with BET inhibitors, such as OTX015 or ABBV-744, in combination with chemotherapeutic agents like DDP or gemcitabine, significantly inhibits tumor growth and enhances the sensitivity of BLCA cells to chemotherapy." (PMID 39551759, 2024). "KLF16 is an oncogene in bladder cancer due to its inhibition of TGF-β receptor 3, which inhibits tumor proliferation by a non-canonical TGF-β pathway." (PMID 36761967, 2023).
cancer (6 papers, 2022 to 2025). A tumor composed of atypical neoplastic, often pleomorphic cells that invade other tissues. "Despite emerging studies suggesting a critical role for KLF16 in cancers, the underlying mechanisms and potential therapeutic targeting strategies are not well understood." (PMID 39551759, 2024). "The high expression of KLF16 continuously promotes the proliferation and invasion of cancer cells and induces angiogenesis." (PMID 41316360, 2025). "Among the candidate genes, we focused on KLF16, as its role in human cancers remains poorly explored." (PMID 39551759, 2024). "KLF16 overexpresses in oral squamous carcinoma and silencing this factor blocks cancer cells in the G0 and G1 phases." (PMID 36761967, 2023). "KLF16 downregulation inhibited the proliferation and migration of cancer cells, decreased the number of G2/M phase cells, and promoted apoptosis in H1299 and H1975 cells." (PMID 35387557, 2022). "KLF16, as a carcinogenic factor, has been confirmed in various cancer-related studies." (PMID 41316360, 2025). "Therefore, LEF1-AS1 is highly likely to upregulate KLF16 by sponging miR-328-5p, and ultimately promote the cancer phenotype." (PMID 41316360, 2025). "The role of KLF16 in cancer cell apoptosis has been a significant area of research in recent years." (PMID 36761967, 2023). "Moreover, The expression of KLF16 was significantly upregulated in ccRCC tissues vs. adjacent non-carcinoma tissues." (PMID 36639679, 2023). "KLF16 is involved in the progression of various cancer types." (PMID 35387557, 2022). "Besides, dysregulation of KLF16 has also been reported to play a critical role in the development of several types of cancer such as prostate cancer, breast cancer, gastric cancer, pancreatic cancer, and anaplastic thyroid carcinoma." (PMID 35387557, 2022).
KLF16 also shares sentences with these, for which no sentence is quoted: colorectal carcinoma (1 paper); Fanconi anemia (1); fatty liver disease (1); Hyperglycemia (1); neuroblastoma (1); renal cell carcinoma (1); triple-negative breast carcinoma (1).